SOX11 (SRY-box transcription factor 11)
Diseases named in the same sentence as SOX11 in open-access papers (continued):
Sharing a sentence is not in itself a finding about the gene and the disease.
breast carcinoma (continued). "Here, we investigated the role of SOX11 in breast cancer progression after tumour formation using a doxycycline-inducible EF1A promoter to express SOX11 in DCIS.com cells at a level comparable to that observed in clinical DCIS and breast cancer samples." (PMID 32909943, 2020). "As with SOX11, both distant metastasis-free survival and overall survival of breast cancer patients are reduced when high levels of TUBB3, an established SOX11 target in neural cells, are expressed in primary tumours." (PMID 32909943, 2020). "Both distant metastasis-free survival and overall survival of breast cancer patients are reduced when high levels of MEX3A are expressed in primary tumours, as would be expected for a SOX11 target." (PMID 32909943, 2020). "In fact, previous studies have found that SOX11 promotes tumor progression in MCL, melanoma and breast carcinoma." (PMID 30922366, 2019). "For instance, Sox12, together with Sox11 and Sox4, is a member of the SoxC TF family, of which Sox4 has an established role in EMT and breast cancer progression." (PMID 29079737, 2017). "A number of candidate effectors of SOX11 signalling in DCIS were identified, including ALDH1A1 and HORMAD1, which have established links to breast cancer." (PMID 28707729, 2017). "SOX4 has been shown to function cooperatively with SOX11 during neuronal development and is also a regulator of EMT in breast cancer." (PMID 26894864, 2016). "Taken together, these results identify SOX11 as a critical regulator of gene expression in BLBC and a promising target for the treatment of these aggressive breast cancers." (PMID 26894864, 2016). "SOX11 and TPX2 showed consistent upregulation of twofold or greater in PR- breast cancers across datasets." (PMID 23506684, 2013). "In the human breast cancer cell line MCF10DCIS.com, MEX3A and MEX3B could be identified among the 25 most upregulated targets due to SOX11 overexpression." (PMID 34067172, 2021). "In brief, the analytical data suggest that SOX11, PLK1, and BUB1 may be involved in tumorigenesis to improve OS of patients with Basal-subtype breast cancer." (PMID 33644115, 2021). "However, in mouse models of breast cancer, MEX3A upregulation was induced by SOX11, a member of the SOXC transcription factors, consisting of SOX4, SOX11 and SOX12." (PMID 34067172, 2021). "In this study, Brca1.3 cells from the control cohort displayed enhanced mammary tumour-initiating activity and cells in tumour spheroids appeared to be in a non-proliferative state compared to cells with lower Sox11 levels." (PMID 33969421, 2021). "The regulation of N-CADHERIN (CDH2) by SOX11 is significant since CDH2 promotes motility in human breast cancer cells regardless of their E-CADHERIN expression." (PMID 32909943, 2020). "SOX11 expression is enriched in ER- and HER2+ invasive breast cancers." (PMID 32909943, 2020). "SOX11 was one of the transcription factors found to have higher expression in TNBC compared to non-TNBC, but a detailed analysis of SOX11 expression in normal breast and breast cancer subtypes had not been performed." (PMID 26894864, 2016). "Interestingly, Sox11 is a transcriptional regulator upregulated in BRCA1-mutant breast cancers and has been shown to promote cell survival and proliferation in breast cancer cells." (PMID 26429062, 2015). "SOX11 levels were higher in basal-like and HER2+ breast cancers compared with other subtypes." (PMID 23506684, 2013). "A trend exists for reduced distant metastasis-free survival in patients with breast cancers expressing higher levels of SOX11, but is not statistically significant." (PMID 23506684, 2013). "Among them, the transcription factor, SOX11, a progenitor cell and lineage regulator of nonmammary cell types, is found highly expressed in some Brca1-/- mammary tumors." (PMID 23506684, 2013).
breast carcinoma (continued). "SOX11, PLK1, BUB1, OGN, COL4A6, AGTR1, and ADRB2 may be involved in the recurrence of Basal-subtype breast cancer, and to some extent the PLK1, BUB1, OGN, COL4A6, AGTR1, and ADRB2 can be used as the specific prognostic markers for Basal-subtype breast cancer." (PMID 33644115, 2021). "This raises the possibility that the reduction in K8, K18 and K14 expression detected in mammary tumours with lower Sox11 levels is due to a lack of activation of an epidermal differentiation programme, and these tumours lack the capacity to form differentiated cells." (PMID 33969421, 2021). "SOX11 is a unique transcription factor, since it does not appear to be expressed in normal mammary epithelial cells after birth in either mouse or human and therefore is well-poised to reactivate developmental pathways when expressed in breast cancers." (PMID 32909943, 2020). "To investigate the role of SOX11 in breast cancer progression, we used the pINDUCER21 system to stably transduce DCIS.com cells, an invasive cell line from the MCF10A breast cancer progression series, so that SOX11 was expressed only when induced with Doxycycline (DOX) (referred to as iSOX11 cells)." (PMID 32909943, 2020). "We have not determined whether SOX11 localises to the cytoplasm, as well as the nucleus, in breast cancer case samples, and if SOX11 localisation could be useful for classification of breast cancers." (PMID 32909943, 2020). "The transcription factor SOX11, potentially of prognostic value but not initially identified in the STRING analysis, has previously been shown to have a role in breast cancer growth and invasion, and in regulating the basal-like phenotype." (PMID 31139569, 2019). "We detected SOX11 expression in triple‐negative [ER–/progesterone receptor (PR)–/HER2–] and HER2+ breast cancer cell lines." (PMID 28707729, 2017). "One network component, SOX11, is not detected in the normal mature postnatal breast, and is highly expressed in basal‐like and HER2+ breast cancers." (PMID 28707729, 2017). "Sox11 is an embryonic mammary epithelial marker that is normally silent in postnatal mammary epithelial cells and is expressed in some oestrogen receptor-negative (ER−) and HER2+ breast cancers." (PMID 33969421, 2021).
Coffin-Siris syndrome (24 papers, 2016 to 2025). Coffin-Siris syndrome (CSS) is a rare congenital multi-systemic genetic disorder characterized by aplasia or hypoplasia of the distal phalanx or nail of the fifth digit, developmental delay, intellectual disability, coarse facial features, and other variable clinical manifestations. "The latest literature reports depict patients exhibiting a phenotype typical for PTHS but with variations in the SOX11 variant (causing Coffin–Siris syndrome)." (PMID 38731134, 2024). "De novo SOX11 heterozygous mutations have been shown to cause intellectual disability, growth deficiency, and dysmorphic features compatible with mild Coffin-Siris syndrome." (PMID 36891511, 2023). "Here we report for the first time on the maternal transmission of mild Coffin–Siris syndrome (CSS) caused by a SOX11 missense variant." (PMID 33785884, 2022). "Kleefstra syndrome, a neurodevelopmental disorder characterised by impaired memory, autistic features and intellectual disability, shares several clinical traits with an SOX11 deficiency disease: Coffin-Siris syndrome." (PMID 33658318, 2021). "SOX11 is mutated in Coffin-Siris syndrome and is a likely candidate for 2p25.2 deletion syndrome; these disorders are characterised by microcephaly with hindbrain abnormalities." (PMID 33658318, 2021). "The group of non-acquired systemic diseases included a Weill–Marchesani case with LTBP2 mutation, a patient with Coffin–Siris syndrome with SOX11 mutation, and one case with Sturge–Weber syndrome." (PMID 35011756, 2021). "The relevance of SOX11 to human developmental disorders was suggested by a recent report of SOX11 mutations in two patients with Coffin–Siris syndrome." (PMID 26543203, 2016). "De novo Sox11 mutations cause Coffin-Siris syndrome, a congenital disorder characterized by microcephaly and intellectual disability." (PMID 27716060, 2016). "A SOX11 variant was identified in one patient (13%) with Coffin–Siris syndrome." (PMID 35011756, 2021). "However, Sox11 homozygous mutant mice normally die soon after birth 10, which hinders the study of the pathogenic mechanism of Coffin-Siris syndrome using mice as models." (PMID 33061816, 2020). "Mutations in SOX11 were found to be causal for Coffin-Siris Syndrome, a congenital disorder associated with intellectual disability and microcephaly, which illustrates the importance of SOX11 for human CNS development and underlines the need to understand SOX11’s regulation." (PMID 29973868, 2018). "The neurodevelopmental phenotypes elicited by Sox11 loss- and gain-of-function in mice as well as the causal link between Sox11 haplo-insufficiency and the intellectual disability associated Coffin-Siris Syndrome underline the importance to precisely regulate SOX11 activity." (PMID 29973868, 2018). "It was proposed that deletion or point mutation of SOX11 may be associated with Coffin-Siris syndrome, a congenital neurodevelopmental disorder, which results in cranial and skeletal malformations." (PMID 29371932, 2017). "Intriguingly, mutations in SoxC proteins, Sox4 and Sox11, are associated with a developmental disorder called Coffin-siris syndrome (CSS), and one key characteristic of CSS patients is craniofacial defects." (PMID 39005444, 2024). "Interestingly, 11/12 mutations could be detected in at least one parent, which means that in the presented sample only one de-novo mutation was found (SOX11-related Coffin–Siris syndrome)." (PMID 35011756, 2021). "Thus, the sox11am/m mutant zebrafish may be helpful for finding the target gene of sox11 and it also is an adequate model for further studying the pathogenic mechanisms of Coffin-Siris syndrome." (PMID 33061816, 2020). "SOX4- and SOX11-related syndromes often share some common features with Coffin–Siris syndrome, which is characterized by abnormal head size (microcephaly or macrocephaly) with characteristic facial features, digits, and eye abnormalities." (PMID 38094004, 2023).
Coffin-Siris syndrome (continued). "Severe congenital ophthalmological malformations and glaucoma might be an important occasional feature in patients with Coffin-Siris syndrome (CSS), especially Coffin-Siris syndrome 9 (CSS9, OMIM #615866) caused by SOX11 mutation." (PMID 33430815, 2021). "In particular, mutations in Sox4 and Sox11, most of them being point mutations in the HMG box, are associated with a developmental disorder called Coffin-siris syndrome (CSS)." (PMID 39005444, 2024). "SOX4 and SOX11 are BAF-complex targets, which accounts for why SOX4- and SOX11-related syndromes are similar to Coffin–Siris syndrome." (PMID 38094004, 2023).
glioma (24 papers, 2007 to 2024). A benign or malignant brain and spinal cord tumor that arises from glial cells (astrocytes, oligodendrocytes, ependymal cells). "In this study, we investigated the suitability of the transcription factor SOX11, a known glioma-associated antigen, as another promising target antigen for immunotherapy." (PMID 36768267, 2023). "The aim of this study was to investigate the suitability of SOX11 peptides as a target antigen for the immunotherapy of glioma." (PMID 36768267, 2023). "In a previous study, the SOX11-derived peptide LLRRYNVAKV was considered as a potential HLA-A*0201 ligand to induce glioma-specific CD8+ T cells." (PMID 36768267, 2023). "SOX11 is a tumor suppressor in glioma and prognostic marker in epithelial ovarian cancer among other roles." (PMID 30281678, 2018). "In line with this research, a previous study has shown that glioma can be converted to post-mitotic neurons via the forced expression of neural reprogramming factors such as Ngn2 and Sox11." (PMID 29161257, 2017). "Together, these data indicate that the synergistic action of NGN2 and SOX11 is required for highly efficient conversion of human glioma cells into neuron-like cells." (PMID 25321470, 2014). "When examined at 5 weeks posttransplantation, very interestingly, some of the NGN2/SOX11-infected (indicated by GFP coexpression) human glioma cells acquired a neuron-like morphology and expressed the pan-neuronal marker TUJ1." (PMID 25321470, 2014). "Accompanying the dramatic reduction of BrdU+ cells was the quick adoption of neuron-like elongated morphology of NGN2/SOX11-expressing glioma cells." (PMID 25321470, 2014). "This was in stark contrast to small tumor masses that were observed in brains injected with NGN2/SOX11 virus-infected glioma cells." (PMID 25321470, 2014). "This explains why brain tumors developed in mice engrafted with human glioma cells that were infected with virus expressing NGN2/SOX11." (PMID 25321470, 2014). "Our results demonstrate that ectopic expression of NGN2 and SOX11 can synergistically and efficiently convert human glioma cells into postmitotic neuron-like cells, which ultimately lose their tumorigenic capacity." (PMID 25321470, 2014). "The most interesting finding is that direct injection of NGN2/SOX11-expressing virus into preexisting brain tumors can reprogram glioma cells in vivo and lead to prolonged survival." (PMID 25321470, 2014). "Taken together, these data indicate that forced expression of NGN2/SOX11 efficiently induces neuronal conversion of glioma cells and that it leads to rapid cycle exit and inhibition of cell proliferation and growth." (PMID 25321470, 2014). "Here, we show that neurogenin 2 (NGN2, also known as NEUROG2) synergizes with sex-determining region Y-box 11 (SOX11) to very efficiently convert human glioma cells to terminally differentiated neuron-like cells in both cell culture and adult mouse brains." (PMID 25321470, 2014). "By 21 dpi, >95% of NGN2/SOX11-infected glioma cells had been converted into neuron-like cells, based on the expression of either TUJ1 or MAP2." (PMID 25321470, 2014). "In sharp contrast, the combinatorial expression of NGN2 and SOX11 converted >95% of virus-transduced human glioma cells into TUJ1+ neuron-like cells." (PMID 25321470, 2014). "The lack of tumorigenic GFP+ cells in the brains engrafted with NGN2/SOX11-expressing glioma cells suggested that they stopped proliferation after transplantation." (PMID 25321470, 2014). "Two days post infection with lentivirus expressing either the control GFP or NGN2/SOX11, the U251 glioma cells were switched to neuronal induction medium supplemented with FSK and DM." (PMID 25321470, 2014). "Human U87 glioma cells were infected with lentivirus expressing either the control GFP or NGN2/SOX11." (PMID 25321470, 2014).
glioma (continued). "Most importantly, intracranial injection of NGN2- and SOX11-expressing virus into the tumor mass also curtails glioma growth and significantly improves survival of tumor-bearing mice." (PMID 25321470, 2014). "Several studies have recently demonstrated that SOX11 is up-regulated in various solid tumors, such as lymphoid neoplasms, gliomas and epithelial ovarian tumors." (PMID 24188789, 2013). "Hide detected that over-expression of SOX11 prevents tumorigenesis of human glioma initiating cells." (PMID 24188789, 2013). "SOX11 up-regulation has been detected in various types of solid tumors, such as gliomas and epithelial ovarian tumors." (PMID 24188789, 2013). "SOX11 has recently been shown to have important diagnostic and prognostic value in MCL, EOC and glioma." (PMID 22738398, 2012). "Moreover, SOX11 demonstrates a notably higher expression in brain cancer compared with other cancer types, underscoring its specific involvement in glioma pathology and its potential as a target for therapeutic interventions in this cancer subtype." (PMID 39457550, 2024). "SOX11 was previously reported in a varying number of glial neoplasms, ranging from 93–100% of astrocytomas, using polyclonal antibody, to a more limited 50% of gliomas when monoclonal antibody MRQ-58 was used." (PMID 37568909, 2023). "However, the overexpression of SOX11 prevents tumorigenic ability in glioma-initiating cell-like cells and human glioma-initiating cells derived from malignant gliomas by inducing neuronal differentiation." (PMID 36524115, 2022). "Sox11 mRNA is significantly more expressed in gliomas compared with healthy brain tissue, suggesting that SOX11 might play a role in malignant transformation and probably cell survival." (PMID 26949534, 2016). "Interestingly, forced expression of NGN2/SOX11 induced glioma cells to rapidly lose their pleomorphic or epithelial morphology and adopt a bipolar appearance as early as 5 dpi." (PMID 25321470, 2014). "We examined whether neuronal conversion of glioma cells by NGN2/SOX11 changed their growth characteristics, as neurons are normally postmitotic." (PMID 25321470, 2014). "Interestingly, neuron-like cells begin to appear as early as 5 dpi of glioma cells with NGN2/SOX11-expressing virus." (PMID 25321470, 2014). "The induction of MAP2 expression by NGN2/SOX11 in these glioma cells followed a similar pattern." (PMID 25321470, 2014). "However, a majority of the NGN2/SOX11-infected human glioma cells seemed to undergo cell death, indicated by pyknosis or fragmented cell bodies." (PMID 25321470, 2014). "Ectopic expression of NGN2/SOX11 in glioma cells results in inhibition of cell proliferation." (PMID 25321470, 2014). "Rapid cell cycle exit of NGN2/SOX11-expressing glioma cells suggests that these cells might also lose their ability to generate tumors in vivo." (PMID 25321470, 2014). "When human glioma cells were transplanted into the mouse striatum 2 dpi with NGN2/SOX11-expressing lentivirus, they could be converted into neuron-like cells in vivo." (PMID 25321470, 2014). "As GFP-negative cells were still proliferating in the brains transplanted with glioma cells that were infected with NGN2/SOX11-expressing virus, we examined the time course of tumor growth by measuring areas containing human glioma cells at 7, 14, and 21 days posttransplantation." (PMID 25321470, 2014). "More recently, we identified SOX11 to be specifically overexpressed in the vast majority of malignant gliomas and demonstrated the generation of SOX11 peptide-reactive CTLs that were capable of lysing HLA-matched glioma cell lines." (PMID 17375044, 2007). "Therefore, the SOX11-derived peptide FMACSPVAL may serve as an epitope for a T cell-based immunotherapy for glioma." (PMID 36768267, 2023). "As our previous work showed that NGN2 and SOX11 can cooperatively reprogram human fibroblasts to postmitotic neurons with high efficiency, we hypothesized that this reprogramming process might also work on glioma cells." (PMID 25321470, 2014).